TRAJ28 (T cell receptor alpha joining 28)
Gene: T-cell receptor joining (J) gene on chromosome 14 (22,515,623 to 22,515,688, forward strand). Ensembl gene ENSG00000211861.
Diseases named in the same sentence as TRAJ28 in open-access papers:
TRAJ28 is named in the same sentence as 1 disease in open-access papers, as found by Europe PMC text mining. Sharing a sentence is not in itself a finding about the gene and the disease. The quoted sentences say what the papers report.
narcolepsy (1 paper, 2023). A sleep disorder characterized by a tendency for excessive sleepiness during the day which occurs even after adequate sleep in the nighttime. "A logical explanation for this observation could be that a TCR-mediated reactivity that involves receptors containing TRAJ24F, TRAJ28 and TRBV4-2 is an important step in the development of narcolepsy, perhaps through TCR recognition of a viral trigger or an autoantigen by CD4+ or CD8+ cells." (PMID 37188663, 2023).